MTOR (mechanistic target of rapamycin kinase)
Diseases named in the same sentence as MTOR in open-access papers (continued):
Sharing a sentence is not in itself a finding about the gene and the disease.
mesothelioma (continued). "Our previous reports implicate AXL overexpression, activation, and regulation of downstream intermediates including PI3K/AKT/mTOR and RAF/MAPK in mesothelioma tumorigenesis." (PMID 32992696, 2020). "VS-5584 is a novel, highly selective dual PI3K/mTOR inhibitor and has obtained the Food and Drug Administration (FDA, USA) approval as orphan drug for mesothelioma patients." (PMID 29514683, 2018). "Recently, it was shown that the combination of rapamycin or PI3K/mTOR inhibitors and one specific RTK inhibitor (EGFR, MET or IGF1R inhibitor) suppressed adverse AKT activation and hampered mesothelioma cell growth in vitro and in MPM xenografts." (PMID 29755689, 2018). "We also found that the combined use of rapamycin and crizotinib was more effective than rapamycin as single-agent in suppressing tumor growth in a patient-derived mesothelioma graft with co-activated ALK and mTOR pathways." (PMID 29755689, 2018). "Here, we studied the combinatorial therapeutic efficacy of the MET/ALK inhibitor crizotinib, with either a pan-class I PI3K inhibitor, BKM120, or with a PI3K/mTOR dual inhibitor, GDC-0980, in mesothelioma." (PMID 27623107, 2016). "In this study, we have identified subsets of mesothelioma that are sensitive to GDC-0980, a novel dual PI3K/mTOR inhibitor currently in clinical trials." (PMID 26284517, 2015). "Here we determined the combinatorial therapeutic efficacy of a new generation small molecule inhibitor of MET, ARQ 197, and dual PI3K/mTOR inhibitors NVP-BEZ235 and GDC-0980 in mesothelioma cell and mouse xenograft models." (PMID 25221930, 2014). "In particular, we found proteins involved in the regulation of pathways aberrantly activated in mesothelioma, such as MAPK, PI3K-Akt and mTOR signalling pathways, as well as the EGFR, Hippo, epithelial to mesenchymal transition and NF-kappa B signalling pathways." (PMID 35987988, 2022). "Rapamycin, an mTOR inhibitor, can inhibit proliferation of NF2-altered mesothelioma cells in vitro." (PMID 36138075, 2022). "Our previous published data had demonstrated overexpression and activation of AXL in mesothelioma cell lines and biopsy materials, which regulates tumor proliferation via PI3K/AKT/mTOR and RAF/MAPK signaling pathways, and AXL expression was stronger in mesothelioma than in the other tumor types." (PMID 32992696, 2020). "It was also shown that baicalin could suppress cell survival, migration, and invasion of mesothelioma cell lines, while sensitizing the cells to chemotherapeutic agents through inhibiting the PI3K/AKT/mTOR signaling pathway." (PMID 33585556, 2020). "The PI3K/mTOR pathway is also highly activated in mesothelioma, but not in non-malignant mesothelial cells or adjacent tissue, and phospho-mTOR was significantly associated with poorer overall survival in a cohort of 107 mesothelioma patients." (PMID 31632972, 2019). "In addition, SIRT1 has been shown to play a role in mTOR, AKT, and ER beta signaling in mesothelioma." (PMID 31608237, 2019). "Given the emerging role of mTOR in mesothelioma development and proliferation, mTOR inhibitors are thought to be promising drugs against merlin-negative mesothelioma." (PMID 29587439, 2018). "In the present work, we demonstrate that GDC-0980 is active in a subset of mesotheliomas, regardless of the activation of the Akt/mTOR pathway." (PMID 26284517, 2015). "IC50 of Mesothelioma cell lines with MET and PI3K/mTOR inhibitors." (PMID 25221930, 2014). "IGF-I signalling in mesothelioma cells drives cell proliferation, motility, and tumourigenesis through its ability to activate cap-mediated protein translation complex through PI3K/Akt/mTOR signalling." (PMID 19603014, 2009). "Besides, as expected from the observed TNT stimulatory effect of PI3K/Akt/mTOR signaling, inhibition of mTOR activity, by rapamycin or by the rapamycin derivative everolimus, suppressed TNT formation in murine astrocytes and human mesothelioma MSTO-211H cells, respectively." (PMID 35267518, 2022).
mesothelioma (continued). "On the other hand, no activating mutations in the MTOR, nor the RHEB genes, have been identified in mesothelioma cells to date, although such mutations were shown to cause the hyper-activation of mTORC1 observed in mesothelioma." (PMID 29587439, 2018).
angiomyolipoma (50 papers, 2009 to 2025). A neoplasm with perivascular epithelioid cell differentiation often associated with tuberous sclerosis. "The primary treatment for parenchymal lung disease due to sporadic LAM is sirolimus, an inhibitor of the mTOR signaling pathway, which has been shown to reduce loss of lung function, chylous accumulation, and angiomyolipoma growth." (PMID 39659355, 2024). "Studies have consistently reported that mTOR inhibitors are associated with controlling the growth of angiomyolipoma, reducing both its size and the risk of bleeding and the need for surgical intervention, while preserving renal function with a relatively low incidence of serious adverse effects." (PMID 38991206, 2024). "The appearance of AMLs in MRI was associated with a rapidly decreasing vascularization of angiomyolipomas and could represent a novel early indicator of response to mTOR inhibitor therapy in this patient collective." (PMID 29232371, 2017). "All modalities can be used.Consider maintaining the use of mTOR inhibitors for dialysis patients to prevent angiomyolipomas bleeding in native kidneys and, if necessary, control other manifestations of the disease." (PMID 38991206, 2024). "Patients with tuberous sclerosis complex (TSC) develop renal cysts and/or angiomyolipomas (AMLs) due to inactive mutations of either TSC1 or TSC2 and consequential mTOR hyperactivation." (PMID 39333852, 2024). "The highest use of systemic mTOR inhibitor was observed for angiomyolipoma (16.4%) followed by focal seizures (13.1%)." (PMID 36104799, 2022). "Immunohistochemistry studies showed low expression of tuberin (TSC2) in angiomyolipoma, which contains activated mTOR signals, compared to healthy kidneys, authenticating the suppression role of TSC2 on mTOR activity." (PMID 36422197, 2022). "Increasing evidence supports the idea that angiomyolipoma is the prototype of lesions in which the mTOR pathway is hyperactivated due to TSC1/TSC2 gene alterations." (PMID 34069976, 2021). "Of note, the expression of cathepsin K in osteoclasts is regulated by MiTF, a transcription factor expressed in angiomyolipoma, which is significantly reduced by mTOR inhibitors." (PMID 34069976, 2021). "42% of patients were treated with mTOR pathway inhibitors, and presence of an angiomyolipoma was the main indication." (PMID 34059113, 2021). "There are several cases of malignant angiomyolipoma which exhibit transient responses to mTOR inhibitors, forming the basis of current practice guidelines in malignant PEComa." (PMID 30285856, 2018). "These recommendations also advocate the use of mTOR inhibitors as first-line treatment in asymptomatic cases of growing angiomyolipomas (> 3 cm in diameter) and selective embolization or kidney-sparing resection as second-line therapy." (PMID 29701176, 2018). "This unconventional case was also noticed in angiomyolipoma cells and interpreted by TSC2/mTOR signaling deficiency." (PMID 29952716, 2018). "Randomized controlled trials have shown that mTOR inhibitors such as sirolimus and everolimus stabilize lung function and reduce angiomyolipoma size in LAM patients." (PMID 30279475, 2018). "Compared to baseline, a significant reduction in angiomyolipoma size was already detected in the group with less than three months of mTOR inhibitor therapy." (PMID 29232371, 2017). "An mTOR inhibitor is the recommended first-line therapy for asymptomatic, growing angiomyolipoma > 3 cm in diameter." (PMID 28057044, 2017). "Emerging strategies targeting the PI3K/AKT/mTOR pathway have been shown to reduce the size of angiomyolipomas and are now used to treat asymptomatic cases >3 cm." (PMID 27525138, 2016). "Recently, two prospective open-label clinical trials in patients with LAM and angiomyolipoma found that the mTOR inhibitor sirolimus reduced angiomyolipoma volume." (PMID 24504542, 2014).
angiomyolipoma (continued). "In the present study, we investigated the role of tuberin/mTOR in regulating N-cadherin and vimentin as major fibrosis proteins involved in the progression and development of angiomyolipomas in TSC patients." (PMID 25149531, 2014). "Since the response to mTOR inhibitors in Tsc2+/- mice correlates well with observations in rapamycin kidney angiomyolipoma trials, it would be reasonable to test this dosing strategy in future TSC clinical trials." (PMID 20146790, 2010). "Our data show that phosphorylation of S6 Kinase at Thr389 was significantly higher in angiomyolipomas tissues compared to control samples indicating the increase of mTOR activity in tumor tissues." (PMID 19265534, 2009). "Early clinical trials show that TSC-related kidney tumors (angiomyolipomas) regress when treated with the mammalian target of rapamycin (mTOR) inhibitor, rapamycin (also known as sirolimus)." (PMID 19368729, 2009). "Angiomyolipoma (AML) is a mesenchymal neoplasm caused by insufficient or defective activation of the TSC1 or TSC2 genes, which leads to uncontrolled activation of the mammalian target of rapamycin (mTOR) pathway." (PMID 41227201, 2025). "From a renal perspective, mTOR inhibitors promote growth control and hinder the progression of angiomyolipoma, reducing the need for surgical and invasive interventions such as nephrectomy and repeated embolizations, which lead to loss of renal mass and function." (PMID 38991206, 2024). "In contrast to the convincing data on the efficacy of mTOR inhibitors in patients with angiomyolipoma, the efficacy of these agents in the treatment of renal cystic disease associated with TSC has yet to be fully defined, but they have shown promising results in recent research." (PMID 38991206, 2024). "Likewise, embolization or nephron sparing surgery to prevent angiomyolipoma bleeding and mTOR inhibitors to prevent tumour growth are effective and detecting angiomyolipoma is similarly important." (PMID 38532450, 2024). "mTOR was known to be involved in the pathogenesis of angiomyolipoma (both in syndromic and non-syndromic scenarios), but mutations in genes that regulate this pathway (TSC1, TSC2, and MTOR) were also rarely found in some common renal tumors, such as ChRCC, clear cell RCC, and papillary RCC." (PMID 37845471, 2023). "mTOR inhibitors, which have the ability to decrease the number of LAM cells in blood and urine, are recognized as therapeutic agents for the prevention of angiomyolipoma growth and kidney function loss." (PMID 29308833, 2017). "The median time from identification of angiomyolipoma to a clinically significant renal event, defined as referral for embolization or surgery, mTOR inhibitor treatment, bleeding or other tumour symptom, was 34 years for patients with sporadic LAM and 25 years for TSC-LAM (range 0–43)." (PMID 25277108, 2014). "The upregulation of mammalian target of rapamycin (mTOR) signaling in angiomyolipoma cells was confirmed by WB, real-time reverse transcriptase-PCR (RT-PCR), and global transcriptomic analysis of angiomyolipoma and angiomyolipoma-derived cells vs. the corresponding normal kidney." (PMID 29184052, 2017). "As some patients with TSC also required mTOR inhibitor treatment for angiomyolipoma, patients with TSC-LAM were more likely to be treated with an mTOR inhibitor overall." (PMID 38532450, 2024). "Fifty-three percent required treatment with an mTOR inhibitor, 36% with sirolimus for LAM and 17% with Everolimus for angiomyolipoma." (PMID 38532450, 2024). "Since activation of mTOR is the driver of TSC tumorigenesis, we assessed the effect of rapamycin (an mTOR inhibitor) on the NSC-like profile of angiomyolipoma cells." (PMID 29184052, 2017). "More recently, pharmacologic inhibition of the kinase mTOR has been shown to reduce angiomyolipoma volume in patients with TSC and sporadic LAM and mTOR inhibitors are now recommended for treatment of angiomyolipoma in TSC." (PMID 25277108, 2014).
angiomyolipoma (continued). "LAM was equally likely to be treated with an mTOR inhibitor with a similar benefit in preventing loss of FEV1 and DLCO although an additional 17% of TSC-LAM patients were receiving an mTOR inhibitor primarily for angiomyolipoma rather than LAM." (PMID 38532450, 2024). "For asymptomatic and growing angiomyolipoma (AML) larger than 3 cm in diameter, therapy with mTOR inhibitors may be the most effective therapy according to some short-duration studies." (PMID 30760308, 2019). "Beyond that, it has not been investigated how mTOR inhibitor therapy affects the different tissue types of angiomyolipoma, vascularization (angio-), myocytes (-myo-) and lipid cells (-lipoma), during the time-course of therapy." (PMID 29232371, 2017). "At the time when angiomyolipomas were detected in our patient, the beneficial effects of mTOR inhibitors had not yet been established and kidney preserving procedures, such as arterial embolization or partial nephrectomy, were not feasible." (PMID 29308833, 2017). "mTOR inhibitors have proven effective in reducing angiomyolipoma (AML) in TSC and total kidney volume in ADPKD but without a positive effect on renal function." (PMID 26077033, 2015). "Despite extensive characterization of the TSC2 pathway in the regulation of mTOR and other downstream signals, the molecular mechanisms that link the biochemical pathway that involve in developing cell fibrosis in TSC patients with angiomyolipoma remain poorly understood." (PMID 25149531, 2014).
cardiomyopathy (50 papers, 2012 to 2026). A disease of the heart muscle or myocardium proper. "The aberrant activation of mTOR in the heart is implicated in the pathogenesis of various cardiomyopathies." (PMID 40002810, 2025). "This study aimed to explore the protective effect of sitagliptin on cardiomyopathy in the type I DM murine model and if its impact is associated with changes in the expression of mTOR, VEGF, and FLT-1." (PMID 40867548, 2025). "Among the detectable markers of cardiomyopathy, we evaluated the activation of mTOR, AKT, Smad3, and ERK1/2 to investigate the association of emerin and lamin A/C in the regulation of signaling pathways associated with cardiomyopathy." (PMID 37940872, 2023). "The present findings demonstrate that in a rat model of T2DM-induced cardiomyopathy, there is evidence of an association between damage of the cardiac contractile unit—sarcomere and desmin—and the iNOS/mTOR/TIMP-1/collagen axis of fibrosis." (PMID 35625721, 2022). "It has been demonstrated that defective mTOR-TFEB signaling is involved in the progression of RagCS75Y mutated cardiomyopathy, which can only be corrected by overexpression of TFEB but not inhibition of mTOR." (PMID 34490237, 2021). "Mice that express H222P-mutated lmna in the heart have elevated AKT and mTOR signaling that leads to cardiomyopathy and impaired fasting-induced autophagy." (PMID 29772801, 2018). "Downstream of the mTOR‐Tfeb axis, fabp7a emerged as a candidate therapeutic target gene for bag3 cardiomyopathy." (PMID 40922543, 2025). "Nevertheless, clinicians have been hesitant to prescribe lifelong mTOR inhibitors because of their immunosuppressive properties and the lack of supporting evidence for mTOR inhibitors efficiency and safety in cardiomyopathy and in patients with ADKH-RRAGD." (PMID 41141537, 2025). "Collectively, these data suggest that cardiomyocyte‐specific overexpression of tfeb recapitulated the therapeutic effects of mTOR inhibition in the bag3 cardiomyopathy model." (PMID 40922543, 2025). "Together, this study uncovered accelerated cardiac senescence as a key pathological event in bag3 cardiomyopathy and reveals that manipulating the mTOR‐Tfeb‐Fabp7a axis can mitigate this pathology and confer cardioprotective effects." (PMID 40922543, 2025). "This study uncovered accelerated cardiac senescence as a key pathological event in bag3 cardiomyopathy, and reveals that manipulating the mTOR‐Tfeb‐Fabp7a axis can mitigate this pathology and confer cardioprotective effects." (PMID 40922543, 2025). "Altogether, these results further demonstrated that FoxO3 protected against DOX‐induced cardiomyopathy through increasing autophagy and suppressing ROS/mTOR activity." (PMID 40785055, 2025). "Remarkably, we observed noteworthy reductions in the ratio of p‐mTOR/mTOR in DOX‐induced cardiomyopathy mice compared to those in the Control group, confirming the mTOR signalling pathway's role in regulating DOX‐induced cardiomyopathy." (PMID 40785055, 2025). "Some studies identified the overactivation of autophagy was involved in the mechanism of DIC and inhibiting autophagy by Akt-mTOR pathway activation protected against DOX-induced cardiomyopathy 26,27." (PMID 38948070, 2024). "Rapamycin, in this context, allowed us to explore the possibility to use a specific inhibitor of the mTOR signaling pathway as a pharmacological treatment for LMNA-related cardiomyopathy." (PMID 35887646, 2022). "Other terms, like NK cell mediated cytotoxicity, Fc gamma R-mediated phagocytosis, Jak−STAT signaling pathway, apoptosis, tight junction, cardiomyopathy, mTOR signaling pathway were also enriched by multiple differentially expressed miRNAs." (PMID 35155276, 2022). "These unexpected results prompted us to investigate why mTOR inhibition was insufficient to exert therapeutic effects in RagCS75Y cardiomyopathy." (PMID 34071043, 2021).